KDELR1 (KDEL endoplasmic reticulum protein retention receptor 1)
Diseases named in the same sentence as KDELR1 in open-access papers:
KDELR1 is named in the same sentence as 18 diseases in open-access papers, as found by Europe PMC text mining. Sharing a sentence is not in itself a finding about the gene and the disease. The quoted sentences say what the papers report.
chondrosarcoma (2 papers, 2024 to 2025). A malignant cartilaginous matrix-producing mesenchymal neoplasm arising from the bone and soft tissue. "KDELR1 expression positively correlates with chondrosarcomas malignancy grade and lower overall survival of patients." (PMID 40767982, 2025). "In summary, KDELR1 modulates chondrosarcoma cell behaviour by regulating the secretion of integrin-α3/β5, thereby influencing YAP1 activity via the RAP2/PLCγ–MAP4K4/LATS1 signalling axis." (PMID 40767982, 2025).
glioma (2 papers, 2022 to 2024). A benign or malignant brain and spinal cord tumor that arises from glial cells (astrocytes, oligodendrocytes, ependymal cells). "Survival analyses showed that gliomas with KDELR1 overexpression were associated with shorter OS and PFS times than gliomas with low KDELR1 expression." (PMID 35814367, 2022). "The results showed that glioma patients with IDH mutation had lower KDELR1 expression than gliomas with IDH wildtype (P < 0.05)." (PMID 35814367, 2022). "As KDELR1 was associated with the prognosis of glioma patients, we wanted to determine whether it was an independent predictor of OS in gliomas using univariate and multivariate survival analyses." (PMID 35814367, 2022). "First, the research on KDELR1 in glioma is still in the early stage, and our research is limited to the bioinformatics database analysis and experimental verification of IHC." (PMID 35814367, 2022). "Correlation, Kaplan–Meier survival, and Cox regression analyses were performed to explore the clinical significance of KDELR1 in glioma patients." (PMID 35814367, 2022). "Taken together, these results indicate that KDELR1 expression is significantly related to the clinical features of gliomas and plays an important positive role in glioma progression." (PMID 35814367, 2022). "To date, several similar molecular classifications of gliomas have been proposed by different research teams; the relationships between their corresponding subtypes and KDELR1 expression were analyzed in this study." (PMID 35814367, 2022). "Cox regression analysis of KDELR1 expression as an independent survival predictor of gliomas in CGGA mRNAseq_325." (PMID 35814367, 2022). "The results from both CGGA mRNA-array_301 and TCGA_glioma showed that KDELR1 was frequently highly expressed in the classical and mesenchymal subtypes and weakly expressed in the proneural and neural subtypes of GBM (P < 0.05)." (PMID 35814367, 2022). "When KDELR1 was submitted to the online tool GEPIA2, survival analyses indicated that glioma samples with KDELR1 overexpression had shorter OS and PFS (progression-free survival) times than those with low KDELR1 expression (P < 0.05)." (PMID 35814367, 2022). "Collectively, Cox regression analyses showed that KDELR1 is an independent prognostic predictor in glioma." (PMID 35814367, 2022). "Using bioinformatics analyses, in this study, we found that KDELR1 expression levels were higher in glioma samples than in the corresponding normal tissues." (PMID 35814367, 2022). "The expression level of KDELR1 was significantly higher in high-grade glioma than in low-grade glioma tissues (p<0.001), which was consistent with the results of bioinformatics analysis at the RNA level." (PMID 35814367, 2022). "Cox regression analysis of KDELR1 expression as an independent survival predictor of gliomas in CGGA mRNA-array_301." (PMID 35814367, 2022). "Cox regression analysis of KDELR1 expression as an independent survival predictor of gliomas in TCGA." (PMID 35814367, 2022). "In this study, genetic and clinical data related to KDELR1 were downloaded from public databases, including TCGA, Gene Expression Omnibus (GEO), and Chinese Glioma Genome Atlas (CGGA)." (PMID 35814367, 2022). "Notably, our research found that KDELR1 is highly expressed in the mesenchymal subtype and expressed at low levels in proneural-subtype gliomas." (PMID 35814367, 2022). "In summary, our findings show that KDELR1 is upregulated in gliomas compared with normal brain tissues and that its expression is significantly associated with clinical features such as the WHO grade, recurrence, molecular classification, IDH mutation, and 1p/19q codeletion status." (PMID 35814367, 2022). "Moreover, similar results in the CCGA mRNA-array_325 and TCGA_glioma datasets showed that KDELR1 expression acts as an independent prognostic predicator in gliomas." (PMID 35814367, 2022).
glioma (continued). "In summary, KDELR1 is strongly related to certain molecular biomarkers and the glioma classification, which indicates that KDELR1 could play a critical role in the development and molecular classification of gliomas." (PMID 35814367, 2022). "On the other hand, KDELR1 expression was associated with immune infiltration (including the infiltration of CD8+ T cells, CD4+ T cells, macrophages, and so on) and microenvironment parameters (including stromal, immune, and ESTIMATE scores) in gliomas." (PMID 35814367, 2022). "In addition, further evaluation confirmed that KDELR1 was closely related to the clinical features of glioma." (PMID 35814367, 2022). "Similarly, mesenchymal-subtype gliomas had a significantly higher expression level of KDELR1 than proneural-subtype gliomas (P < 0.05)." (PMID 35814367, 2022). "KDELR1 expression was positively associated with immune infiltration (including infiltration by CD8+ T cells, CD4+ T cells, macrophages, and so on) and microenvironment parameters (including stromal, immune, and ESTIMATE scores) in gliomas." (PMID 35814367, 2022). "Collectively, these results indicate that KDELR1 could be a promising novel biomarker for molecular classification, immune treatment, and prognostic assessment in glioma." (PMID 35814367, 2022). "Taken together, these findings indicate that KDELR1 might act as a novel promising biomarker for the diagnosis, treatment, and prognosis of gliomas." (PMID 35814367, 2022). "In addition, previous studies have demonstrated that mesenchymal-subtype gliomas are associated with poor prognosis, which are confirmed by our finding that mesenchymal -subtype gliomas had a higher expression level of KDELR1 than proneural subtype gliomas." (PMID 35814367, 2022). "A previous study also suggested that older glioma patients would have a poorer prognosis than younger patients, which indicates that KDELR1 expression levels might possess an indirect clinical value in prognosis." (PMID 35814367, 2022). "In addition, recurrent glioma samples showed a higher expression level of KDELR1 than primary samples in the CGGA mRNA-array_693 dataset (P < 0.05)." (PMID 35814367, 2022). "Moreover, the survival and Cox regression analyses of different datasets suggested that KDELR1 expression in gliomas could be an independent, unfavorable prognostic factor for survival time." (PMID 35814367, 2022). "In addition, survival analysis showed that glioma patients with KDELR1 overexpression had shorter overall survival (OS) and disease-free survival times, and Cox regression analysis revealed that KDELR1 acted as an independent prognostic factor of OS in glioma patients." (PMID 35814367, 2022). "We analysed the protein expression of 12 of the 14 differentially expressed endosomal recycling regulators in this glioma proteomics inventory (CMTM6 and KDELR1 were missing from this dataset)." (PMID 38638676, 2024). "Several datasets showed that KDELR1 expression was higher in glioma patients aged ≥45 years than in those aged <45 years, including mRNA-array_301 and mRNAseq_325 of CGGA, TGGA_glioma, GSE4271, and GSE13041 (GPL96) (P < 0.05)." (PMID 35814367, 2022). "The results showed that KDELR1 expression significantly increased with the WHO grade in several cohorts, including mRNA-array_301, mRNA-array_325, and mRNA-array_693 of CGGA, TCGA_glioma, GSE4271, GSE4290, and GSE4412 (P < 0.05)." (PMID 35814367, 2022). "The ESTIMATE algorithm was performed to assess the immune levels of glioma patients and showed significant differences (p<0.001) in the immune score, stromal score, and ESTIMATE score between the patients with high and low KDELR1 expression." (PMID 35814367, 2022). "Using the information from databases including GEO, CGGA, and TCGA, we wanted to determine whether the expression level of KDELR1 was related to the WHO grade and pathological classification of gliomas." (PMID 35814367, 2022).
glioma (continued). "However, the roles of KDELR1 in the biological functions and molecular mechanisms of gliomas are not clear." (PMID 35814367, 2022). "KDELR1 overexpression frequently occurred in glioma samples without 1p/19q codeletion (P < 0.05)." (PMID 35814367, 2022). "Thus, KDELR1 might be a negative prognostic factor in gliomas from the 1p/19q codeletion perspective." (PMID 35814367, 2022). "Moreover, microvascular proliferation and necrosis are the diagnostic criteria of GBMs, and the analysis of the GSE4271 dataset showed that grade IV gliomas with necrosis or microvascular proliferation had much higher KDELR1 expression than those without necrosis (P < 0.05)." (PMID 35814367, 2022).
melanoma (2 papers, 2020 to 2025). A malignant, usually aggressive tumor composed of atypical, neoplastic melanocytes. "We demonstrate that the embryonic melanoblast gene, KDELR3, is a metastasis enhancer in both mouse and human melanoma cells, whereas KDELR1 suppresses metastasis, despite having extensive homology and similar retrograde-trafficking functions." (PMID 31949145, 2020). "Interestingly, KDELR1 plays an opposing role in melanoma progression, with its knockdown promoting metastasis, suggesting that this receptor functions as an inhibitor of melanoma metastasis." (PMID 40767982, 2025). "Notably, in contrast to KDELR3 knockdown, which predictably diminished metastasis, KDELR1 knockdown actually increased metastasis, suggesting that KDELR1 contributes in a very different way to melanoma etiology and can function as a metastasis suppressor." (PMID 31949145, 2020). "Virtually all melanoma cell lines in the NCI60 were characterized by elevated KDELR3 expression, but reduced or unchanged expression of KDELR1 and KDELR2, respectively." (PMID 31949145, 2020). "KDELR1 and KDELR3 play an oppositive role during melanoma progression." (PMID 40767982, 2025).
astrocytomas (1 paper, 2022). "Similarly, KDELR1 expression was upregulated from control samples to oligodendrogliomas, astrocytomas, and GBMs in the GSE68848 dataset (P < 0.05)." (PMID 35814367, 2022). "Moreover, the expression level of KDELR1 was gradually upregulated along the sequence from control samples to oligodendrogliomas, astrocytomas, and GBMs in the GSE4290 dataset (P < 0.05)." (PMID 35814367, 2022).
COVID-19 (1 paper, 2024). A disease caused by infection with severe acute respiratory syndrome coronavirus 2. "This suggests that autoreactivity to ERFL, SNX8 and KDELR1 is a significant feature of MIS-C that is separable from SARS-CoV-2 exposure and severe acute paediatric COVID-19." (PMID 39112696, 2024).
lung adenocarcinoma (1 paper, 2025). A carcinoma that arises from the lung and is characterized by the presence of malignant glandular epithelial cells. "A recent study also reported a role for KDELR1 in lung adenocarcinoma (LUAD) progression, highlighting its influence on both tumour cell behaviour and the tumour microenvironment." (PMID 40767982, 2025).
lymphopenia (1 paper, 2021). Reduction in the number of lymphocytes. "KDELR1 mutations are also associated with antiviral immunity, with one mutation (Y158C) being associated with lymphopenia, reduced T-cell receptor expression, deficient antiviral immunity, and increased CD44 expression." (PMID 34063979, 2021). "In addition, known mutations in KDELR1 and KDELR2 are associated with lymphopenia and osteogenesis imperfecta, respectively, making KDEL receptor replacement an attractive therapeutic strategy for these conditions." (PMID 34063979, 2021).
neuroblastoma (1 paper, 2016). Neuroblastoma (NB) is the most common solid, extracranial childhood tumor. "Using cell surface biotinylation, we were able to detect KDELR1 at the cell surface of mammalian cells, in agreement with recent studies in which a pool of KDELR1 was observed at the PM of neuroblastoma cells." (PMID 27353000, 2016).
Osteochondroma (1 paper, 2024). A common, benign cartiliginous neoplasm arising from the metaphysis of bone. "Initially, the expression of KDELR1 in CS was examined in 110 samples, comprising osteochondroma specimens (n = 29), and CS specimens with various grades including Grade I (n = 28), Grade II (n = 28), Grade III (n = 25)." (PMID 39715773, 2024).
tumor (5 papers, 2022 to 2025). "Specifically, the expression of all three KDELRs in cancer cells has been associated with immune cell infiltration across various tumour types, with KDELR1 also recognized as a modulator within immune cells themselves." (PMID 40767982, 2025). "Our analysis revealed a specific increase in KDEL receptor 1 (KDELR1) expression in CS, which was closely associated with CS prognosis, tumor aggressiveness, and drug resistance." (PMID 39715773, 2024). "We found that KDELR1 promotes the proliferation, invasion, and migration of tumor cells and that high expression of KDELR1 was associated with poor prognosis in patients with LUADs." (PMID 39101247, 2024). "They found that KDELR1 was highly expressed in CS cells, particularly in high-grade tumours, and that its levels correlated with poor prognosis, higher LR rates and greater metastatic potential." (PMID 41294677, 2025). "Tumours with reduced KDELR1 expression showed slower growth, reduced metastatic activity, and improved response to the CHT drug cisplatin." (PMID 41294677, 2025). "The importance of KDELRs in tumour biology is further underscored by the role of KDELR1 in shaping the immune system." (PMID 40767982, 2025). "To further explore the molecular mechanisms by which USP22‐mediated tumor cell‐derived EVs promote tumor metastasis in LUADs, we identified KDELR1 as a downstream effector of USP22 using gene chip and bioinformatics analyses." (PMID 39101247, 2024). "The results of IF staining showed that the expression of YAP1 was significantly increased in KDELR1-kd tumor xenograft." (PMID 39715773, 2024). "KDELR1 plays a key role in regulating membrane protein processing and secretion, as well as contributing to tumor extracellular matrix (ECM) formation and drug resistance." (PMID 39715773, 2024). "The expression of KDELR1 and its correlation with the tumor grade and prognosis were confirmed by immunohistochemistry in clinical samples (n = 119, P < 0.05)." (PMID 35814367, 2022). "Considering the close relationship between membrane proteins and tumor drug resistance, and KDELR1’s involvement in the process of membrane proteins modification and processing, we further explored how KDELR1 regulates the chemotherapeutic effect of Cisplatin in CS therapy." (PMID 39715773, 2024). "KDELR1 depletion using in vivo‐optimized RNAi significantly weakened tumor growth." (PMID 39101247, 2024). "Finally, gene expression studies have shown that KDELR1 is also overexpressed in gliomas, with its expression positively correlating with tumour grade, recurrence, necrosis, isocitrate dehydrogenase (IDH) mutations, reduced overall survival, and increased infiltration of T cells and macrophages." (PMID 40767982, 2025). "High KDELR1 expression led to reduced phosphorylation of YAP1, allowing it to remain active and drive tumour growth." (PMID 41294677, 2025). "KDELR1 enhanced the USP22‐mediated invadopodia formation and promoted the ability of tumor cells to penetrate the basement membrane in the in vitro metastasis model." (PMID 39101247, 2024). "To better understand the role of KDELR1 in tumorigenesis in vivo, we established USP22 control and overexpression tumor models and intratumoral injection of siRNA for KDELR1 (5 nmol/20 g/mice)." (PMID 39101247, 2024). "KDELR1 knockdown reversed the role of USP22 in promoting invadopodia formation and tumor metastasis." (PMID 39101247, 2024). "Targeting KDELR1 may enhance the efficacy of CHT and inhibit tumour progression by restoring the tumour suppressor activity of the Hippo-YAP1 pathway." (PMID 41294677, 2025).
cancer (4 papers, 2016 to 2025). A tumor composed of atypical neoplastic, often pleomorphic cells that invade other tissues. "In contrast, reducing KDELR1 levels increased YAP1 phosphorylation, causing YAP1 to accumulate in the cytoplasm in an inactive state, thereby suppressing cancer cell growth and improving drug sensitivity." (PMID 41294677, 2025). "The DepMap collection of CRISPR co-dependency data in cancer may offer insights into this question, particularly if KDELR1-3 each has distinct sequence preferences for these retention motifs." (PMID 40867591, 2025). "This KDELR1-initiated signalling stimulates cell proliferation and motility, explaining how KDEL chaperones released by cancer cells can influence cancer progression." (PMID 40767982, 2025). "Introducing an active YAP1 mutant reversed these effects, further demonstrating the importance of KDELR1 in maintaining YAP1 activity and cancer aggressiveness." (PMID 41294677, 2025).
neurodevelopmental disorder (1 paper, 2023). A behavioral and cognitive disorder with onset during the developmental period that involves impaired or aberrant development of intellectual, motor, or social functions. "KDELR1 is also one of the candidate molecules associated with neurodevelopmental disorders, suggesting it may be one of the key molecules associated with the occurrence of AD." (PMID 36915078, 2023).
KDELR1 also shares sentences with these, for which no sentence is quoted: dwarfism (1 paper); fibrosarcoma (1); metastatic melanoma (1); oligodendroglioma (1); osteogenesis imperfecta (1); skin cutaneous melanoma (1).